LRG1 (leucine rich alpha-2-glycoprotein 1)
Diseases named in the same sentence as LRG1 in open-access papers (continued):
Sharing a sentence is not in itself a finding about the gene and the disease.
Crohn disease (13 papers, 2011 to 2025). A gastrointestinal disorder characterized by chronic inflammation involving all layers of the intestinal wall, noncaseating granulomas affecting the intestinal wall and regional lymph nodes, and transmural fibrosis. "Studies in context with other inflammatory conditions such as on adult-onset Still’s disease (AOSD) or Crohn’s disease similarly suggest an association of IL-1β and LRG1 expression." (PMID 35699824, 2022). "More recently, LRG1 was identified as a novel, serum pro-inflammatory biomarker for RA and Crohn's disease." (PMID 22044644, 2011). "In summary, the stricturing and penetrating Crohn’s disease phenotype is characterized by distinct proteomic signatures, evidenced by elevated serum levels of WDR31, LRG1, and SAA1." (PMID 38069288, 2023).
non-small cell lung carcinoma (12 papers, 2015 to 2024). A group of at least three distinct histological types of lung cancer, including non-small cell squamous cell carcinoma, adenocarcinoma, and large cell carcinoma. "The expression of LRG1 is associated with a variety of malignancies, such as non-small-cell lung cancer (NSCLC), ovarian cancer, and bladder cancer, and is thought to promote tumor growth via the angiogenesis process." (PMID 32337221, 2020). "Reports have found that CD317, epidermal growth factor receptor (EGFR) in plasma EVs, and human leucine rich alpha-2-glycoprotein 1 (LRG1) in urinary EVs are reliable biomarkers for diagnosing non-small cell lung cancer (NSCLC)." (PMID 38814362, 2024). "In proteomics-based mass spectrometry analysis, urinary exosomes were remarkably more efficient in expressing leucine-rich alpha-2-glycoprotein 1 (LRG1) in non-small cell lung cancer (NSCLC) cases compared with normal control individuals." (PMID 34980158, 2022). "LRG-1 is also known as a promising tumor biomarker and an independent prognostic factor for endometrial carcinoma and non-small cell lung cancer." (PMID 30760292, 2019). "For exosomes from non-small cell lung cancer, epidermal growth factor receptor (EGFR), placental alkaline phosphatase (PLAP), and leucine-rich alpha-2-glycoprotein 1 (LRG1) proteins were among those found to be overexpressed." (PMID 31069333, 2019). "In patients with non-small cell lung cancer, serum LRG-1 expression was significantly higher than that in healthy volunteers, and LRG-1 was found as an outstanding tool in predicting prognosis and relapse." (PMID 30760292, 2019). "miR-335 appears to control growth by blocking cell proliferation by targeting certain genes; e.g., RASA1 in rat epididymal development, SP1 and Bcl-w in non-small cell lung cancer, SOX4 and TNC in breast cancer, ROCK1, MAPK1, and LRG1 in neuroblastoma, and Rb1 in U2OS osteosarcoma cells." (PMID 26204513, 2015).
type 2 diabetes (12 papers, 2017 to 2024). "Plasma LRG1 level was independently associated with urinary albumin excretion in patients with type 2 diabetes." (PMID 37916147, 2023). "A recent study reported that LRG1 is associated with endothelial dysfunction, arterial stiffness, and peripheral arterial disease in patients with type 2 diabetes." (PMID 29190982, 2017). "A positive association between LRG1 and BMI was also observed in patients with type-2 diabetes." (PMID 35955698, 2022). "Leucine-rich α-2-glycoprotein 1 (LRG1), an upregulated proangiogenic gene in DKD kidney, was found associated with worse renal outcome in patients with type 2 diabetes." (PMID 39258389, 2024). "Patients with type 2 diabetes exhibit elevated plasma LRG1 levels, which seems to be related to the occurrence and progression of diabetic nephropathy and proliferative diabetic retinopathy." (PMID 35562586, 2022). "Pigment epithelial-derived factor and LRG1 mediated a negative association between skeletal muscle mass index and chronic kidney disease in Asians with progression to type 2 diabetes." (PMID 35095520, 2021). "Notably, LRG1 plasma levels correlate with arterial stiffness and reduced vasodilation in patients with type 2 diabetes, which could therefore perhaps be explained by LRG1 tuning of EC TGFβ signalling." (PMID 34987199, 2022). "Thus, it has been shown that in people with type 2 diabetes and DKD, plasma LRG1 levels predict both albuminuria and CKD progression beyond traditional risk factors." (PMID 38745756, 2024).
breast carcinoma (10 papers, 2010 to 2026). "In patients with early breast cancer (BC), high intratumoral LRG-1 protein expression levels are associated with reduced survival." (PMID 38413424, 2024). "Leucine-rich alpha-2-glycoprotein 1 (LRG1) has been linked to tumor progression and angiogenesis, but its molecular mechanisms in breast cancer are poorly defined." (PMID 42074251, 2026). "In breast cancer (BC), LRG-1 has anti-apoptotic potential and its increased tumor tissue expression is associated with worse prognosis and lymph node metastasis." (PMID 38413424, 2024). "Additionally, LRG1 peptides have been identified in the conditioned media of prostate cancer, and breast cancer cell lines and in the peritoneal fluid of women with uterine leiomyomas." (PMID 20831812, 2010). "We have found that MCF-7 breast cancer cells transfected with LRG1 are more resistant to apoptosis induction than non-transfected cells due to cytoplasmic LRG1 binding cytochrome c and inhibition of Apaf-1 activation (Jemmerson and colleagues, manuscript in preparation)." (PMID 20831812, 2010).
COVID-19 (10 papers, 2022 to 2025). A disease caused by infection with severe acute respiratory syndrome coronavirus 2. "Although most of these studies associate elevated LRG1 expression with an early immune and inflammatory response, it is possible that LRG1 exerts an angiopathic role in the pulmonary microvasculature related to COVID-19." (PMID 38745756, 2024). "Elevated levels of circulating LRG1 have also been reported in severe COVID-19 patients in blood, plasma, and tissue proteomic studies." (PMID 38745756, 2024). "Consistent with this possibility, circulating LRG1 levels have been reported to be raised in severe COVID-19 patients and in patients with vasculitis, where vascular damage is a primary feature." (PMID 35318338, 2022). "A proteomic study pointed out that LRG1 upregulated in severe COVID-19 patients as a function of IL-6 levels." (PMID 36091008, 2022). "Following recent findings, showing high circulating LRG1 levels in COVID-19 patients, we propose that IL-6 is driving LRG1 production in the lung resulting in some of the pulmonary vasculopathy observed." (PMID 35318338, 2022). "Elevation of both IL-6 and LRG1 in patients with COVID-19 suggests that circulating pro-inflammatory IL-6 may induce systemic and local upregulation of angiopathic LRG1 in the pulmonary microvasculature." (PMID 38745756, 2024). "We propose, therefore, that direct targeting of LRG1 may be an alternative, or complementary, therapy for COVID-19-related pulmonary microvascular complications and other disease where the vasculature is disrupted by IL-6." (PMID 35318338, 2022). "In the other hand, CD14, LBP and LRG1 might indicate the progression of lung damage in COVID-19 patients." (PMID 35884998, 2022). "Notably, COVID-19 patients have also been found to exhibit significantly enhanced circulating levels of LRG1 that, along with other biomarkers, can distinguish mild from severe disease." (PMID 35318338, 2022). "Our data highlight the potential of using LRG1 as a new therapeutic target to treat conditions with prominent pathological angiogenesis and dysfunctional vessels, such as age-related macular degeneration, cancer, and COVID-19-related pulmonary complications." (PMID 35318338, 2022). "There are also similarities between LD subjects and severe COVID-19 subjects with KNG (pro coagulation-platelet degranulation), LRG1 (antimicrobial), and PROS1 (anticoagulant), which are found in higher abundance in both." (PMID 36569838, 2022).
chronic kidney disease (9 papers, 2020 to 2024). Impairment of the renal function secondary to chronic kidney damage persisting for three or more months. "For example, a study discloses that increased plasma LRG1 is linked with a higher risk of cardiovascular disease in patients with end-stage renal disease." (PMID 38742172, 2024). "In patients with chronic kidney disease, plasma LRG1 level was suggested to be associated with the progression of chronic kidney disease." (PMID 37916147, 2023). "In patients with chronic kidney disease, plasma LRG1 level was suggested to be associated with chronic kidney disease progression." (PMID 37916147, 2023). "Several studies show that in a variety of chronic kidney disease (CKD) models LRG1 gene and protein expression is significantly increased." (PMID 38745756, 2024). "We and others have identified that the concentration of circulating leucine-rich α-2 glycoprotein 1 (LRG1) was increased in diabetic and chronic kidney disease patients." (PMID 38003727, 2023). "Serum LRG1 participated in the prediction of the mortality of cardiovascular morbidity complication in end-stage renal disease patients (Yang FJ." (PMID 35095520, 2021). "LRG1 has been shown to be elevated in the urine of patients with IgA nephropathy and chronic kidney disease." (PMID 33193334, 2020). "This also adds to the debate of whether LRG1 is the cause or the consequence of anemia, since the chronic inflammation observed in the study is closely linked to CKD (chronic kidney disease)." (PMID 37513518, 2023).
colon cancer (9 papers, 2019 to 2025). "Proteomic analysis of the serum-derived EVs unveiled secreted protein acidic and cysteine rich (SPARC) and leucine rich alpha-2-glycoprotein 1 (LRG1) can serve as diagnostic markers for colon cancer and predict tumor recurrence." (PMID 38741166, 2024). "The level of EVs containing SPARC (extracellular matrix) and LRG1 (cell signaling) are higher in the serum from patients with stage III colon cancer than in the serum from healthy control individuals, and they were predictive of disease recurrence." (PMID 36831450, 2023). "Colon cancer patients had significant high level of SCF compared with rectum cancer (p = 0.039) whereas LRG1 levels were significantly elevated in high grade G3 than low grade of CRC (p = 0.05)." (PMID 33492603, 2021). "Since then, more studies on LRG-1 have emerged gradually and LRG-1 is recognized as a new regulator of tumorigenesis and a novel oncogene-associated protein, playing an important role in epithelial-mesenchymal transition (EMT) and angiogenesis in colon cancer." (PMID 30760292, 2019). "This selective increase in SPARC and LRG1 in colon cancer EVs, as opposed to other cancers such as gastric, thyroid, or cervix cancers, underscores the specificity of these markers for colon cancer." (PMID 39370455, 2024). "However, in our study, LRG1 expression in colon cancer tissue was lower than that in normal colon tissue (relative abundance LNMC/NC = 0.668, RNMC/NC = 0.839), although the levels in RNMC were still higher relative to LNMC (RNMC/LNMC = 1.257)." (PMID 34590603, 2021).
melanoma (9 papers, 2015 to 2025). A malignant, usually aggressive tumor composed of atypical, neoplastic melanocytes. "High LRG1 levels have previously been reported as a poor prognostic marker in malignant melanoma and associated with disease relapse in the neoadjuvant setting." (PMID 38777088, 2024). "To establish the association between LRG1 and melanoma, we investigated the expression of LRG1 in human biopsy specimens via immunohistochemistry staining using an LRG1-specific antibody." (PMID 34208965, 2021). "We first established the association between LRG1 and melanoma in both human patient biopsies and mouse melanoma cell lines and revealed a significant induction of LRG1 expression in metastatic melanoma cells." (PMID 34208965, 2021). "We used the xenograft tumour model to establish the cause–effect relationship between Lrg1 and melanoma development." (PMID 34208965, 2021). "In addition, tumor tissue and serum levels of LRG-1 are increased and associated with worse prognosis in numerous malignancies such as melanoma, colorectal, pancreatic, prostate, lung, hepatocellular, and ovarian cancer." (PMID 38413424, 2024). "Here, we show for the first time that systemic LRG1 expression is also increased during melanoma disease progression." (PMID 37089863, 2023). "Second, LRG1 is much enhanced in melanoma cells of malignant melanoma tissue as compared to cells in the stroma." (PMID 34208965, 2021). "Taken together, these data provided compiling evidence that Lrg1 is required for melanoma metastasis into the lungs in vivo." (PMID 34208965, 2021). "As melanoma is highly metastatic, we next investigated the role of Lrg1 in melanoma dissemination to the lungs." (PMID 34208965, 2021). "Overall, our study provided strong evidence of Lrg1’s role in melanoma metastasis and Lrg1 exerting its function through activation of the EGFR/STAT3 signalling pathway." (PMID 34208965, 2021). "We developed a human LRG1 (hLRG1)-expressing B16F0 mouse melanoma cell line and demonstrate that Magacizumab binds to LRG1 and localises to the tumour site." (PMID 34458833, 2021). "Our finding revealed a significant reduction in tumour burden, total tumour nodule area, and melanoma cell extravasation in the lungs of Lrg1-/- mice as compared to wild-type controls." (PMID 34208965, 2021). "Our study demonstrated that LRG1 regulates multiple aspects of melanoma metastasis through modulating EGFR/STAT3 signalling." (PMID 34208965, 2021). "In the present study, we first investigated the expression of LRG1 in human melanoma biopsies and murine melanoma cell lines and established an association between LRG1 and melanoma." (PMID 34208965, 2021). "As melanoma is a highly metastatic disease, we then explored the potential role of Lrg1 in melanoma metastasis." (PMID 34208965, 2021). "Having established a role for Lrg1 in melanoma metastasis, especially the extravasation step, in vivo, we next investigated how Lrg1 modulates melanoma cell function in vitro." (PMID 34208965, 2021). "Together, these results suggest that Lrg1 promotes melanoma cell migration and invasion by activating the EGFR/STAT3 signalling pathway in a Src-independent manner." (PMID 34208965, 2021). "Although expressed at low levels in normal melanocytes, we show for the first time that LRG1 is significantly enhanced in malignant melanoma cells of human melanoma tissues." (PMID 34208965, 2021). "In this study, we investigated the role of leucine-rich α-2-glycoprotein 1 (LRG1) in melanoma development and progression." (PMID 34208965, 2021). "Recently, STAT3 signaling was also reported to be involved in LRG1-promoted metastatic dissemination of melanoma." (PMID 34930899, 2021). "We then determined the role of LRG1 in melanoma growth in a tumour xenograft model as well as in vitro cell-based tumour cell viability and proliferation assays." (PMID 34208965, 2021).
melanoma (continued). "Together, these data demonstrated that Lrg1 promotes tumour cell dissemination by affecting various properties of melanoma cells in both mice and humans." (PMID 34208965, 2021). "Instead, we found that LRG1 promotes melanoma cell migration, invasion, adhesion, and lung metastasis." (PMID 34208965, 2021). "We further confirmed LRG1’s role in tumour cell adhesion to the endothelium, transendothelial migration, invasion, and migration in a human melanoma cell line A375." (PMID 34208965, 2021). "This prompted us to test the impact of Lrg1 on melanoma cell adhesion to ECM." (PMID 34208965, 2021). "Consistent with the in vivo observations, the ability of parental B16F10 cells to adhere to and transmigrate across the HPMEC subjected to siRNA-mediated Lrg1 knockdown was significantly lower, suggesting that both tumour cell and endothelial cell-derived Lrg1 affect melanoma cell extravasation." (PMID 34208965, 2021). "Furthermore, Lrg1 expression levels in the metastatic mouse melanoma cell line B16F10 are significantly higher than those in the parental melanoma cell line B16F0." (PMID 34208965, 2021). "As Lrg1-/- mice are healthy and have a normal life span, unlike mice treated with current STAT3 inhibitors, targeting LRG1 may cause fewer unwanted side effects and offers an alternative strategy to control STAT3-mediated melanoma metastasis." (PMID 34208965, 2021). "However, the biological function of LRG1 in melanoma development and progression remains to be elucidated." (PMID 34208965, 2021). "Mechanistically, LRG1 mediates melanoma cell invasiveness in an EGFR/STAT3-dependent manner." (PMID 34208965, 2021). "We further tested Lrg1 expression in two different murine melanoma cell lines, B16F0 and B16F10." (PMID 34208965, 2021). "Furthermore, STAT3 activation is required for the promoting effect of LRG1 on melanoma cell migration and invasion." (PMID 34208965, 2021). "Next, we performed the Matrigel invasion assay to test the role of Lrg1 in melanoma cell invasion." (PMID 34208965, 2021). "However, further investigations are required to determine whether LRG1 is indeed mechanistically contributing to metastasis formation in patients with melanoma." (PMID 37089863, 2023). "Targeting LRG1 may offer an alternative strategy to control malignant melanoma." (PMID 34208965, 2021). "Targeting LRG1 may offer an alternative way to control the metastatic spread of melanoma cells." (PMID 34208965, 2021). "Finally, the extravasation capability of melanoma cells was studied by inoculating CMFDA Green-labelled B16F10 cells through the tail vein of wild-type and Lrg1-/- mice." (PMID 34208965, 2021). "Targeting LRG1, therefore, may offer an alternative strategy to control STAT3-mediated melanoma metastasis." (PMID 34208965, 2021). "Taken together, our studies provided compelling evidence that LRG1 is required for melanoma metastasis but not growth." (PMID 34208965, 2021). "However, the role of LRG1 in melanoma development and progression has not been established." (PMID 34208965, 2021).
asthma (8 papers, 2016 to 2024). "LRG1 has been suggested as a reliable biomarker for the diagnosis and monitoring of dermatomyositis-associated pneumonia and airway inflammation in asthma." (PMID 35062948, 2022). "Findings in clinical respiratory diseases suggested that LRG1 was a promising biomarker for the detection of active tuberculosis, lung fibrosis, asthma, allergic rhinitis, and asthma." (PMID 35095520, 2021). "The expression levels of LRG1 and its receptor transforming growth factor-beta receptor II (TGFBR2) in patients with allergic rhinitis (AR) and asthma (AS) were examined by flow cytometry, and enzyme-linked immunosorbent assay (ELISA)." (PMID 27378305, 2016). "Locally secreted LRG1 might play a direct role in the pathogenesis of asthma by triggering TGFβ-induced subepithelial fibrosis." (PMID 35062948, 2022). "In a mouse model of ovalbumin-induced asthma, LRG1 was shown by immunohistochemistry to be secreted locally by putative non-ciliated, mucin-producing bronchial epithelial cells, known as goblet cells, which under physiological conditions are not known to express LRG1." (PMID 35062948, 2022). "LRG1 was highly expressed in a subpopulation of bronchial epithelial cells in asthma model mice." (PMID 35095520, 2021).